GON4L (gon-4 like)
Description:
Acts as a key transcription regulator of histones. Activates transcription of the histone H2A, histone H2B, histone H3 and histone H4 genes in conjunction with GON4L and MIZF. Together with CRAMP1, binds to the promoters of H1 genes (H1-2, H1-3, H1-4, H1-5 and H1-10/H1x), driving their transcription. Also acts as a transcription corepressor, as part of a complex with YY1, SIN3A and HDAC1 (By similarity). Required for B-cell lymphopoiesis (By similarity).
Synonyms: GON4; YARP; FLJ20203; GON-4; LTMS
Tractability: PROTAC: ubiquitination databases record sites on it.
Gene: Protein-coding gene on chromosome 1 (155,749,659 to 155,859,400, reverse strand). Ensembl gene ENSG00000116580.
Subcellular location: Nucleus; Chromosome
Subcellular location (Human Protein Atlas): Nuclear bodies; Nucleoplasm
Gene Ontology:
Molecular function: transcription coregulator activity
Biological process: regulation of DNA-templated transcription
Cellular component: chromosome; nuclear body; nucleoplasm; nucleus
Genetic constraint (gnomAD): Loss-of-function variants: 68 observed, 169.8 expected, observed/expected ratio (o/e) 0.4, 90% interval 0.33 to 0.49. The upper end of that interval is the gene's LOEUF score, 0.49, which puts it in group 2 of 6, group 1 being the genes least tolerant of losing a copy. Missense variants: 1,940 observed, 2,393.1 expected, observed/expected ratio (o/e) 0.81, 90% interval 0.78 to 0.84. Synonymous variants: 791 observed, 879.13 expected, observed/expected ratio (o/e) 0.9, 90% interval 0.85 to 0.95.
Homologues: Orthologues: chimpanzee GON4L (99% identical), macaque GON4L (96% identical), guinea pig Gon4l (80% identical), rat Gon4l (75% identical), mouse Gon4l (75% identical). Paralogues in human: YY1AP1 (31% identical).
Diseases named in the same sentence as GON4L in open-access papers:
GON4L is named in the same sentence as 8 diseases in open-access papers, as found by Europe PMC text mining. Sharing a sentence is not in itself a finding about the gene and the disease. The quoted sentences say what the papers report.
dwarfism (1 paper, 2016). "Analysis of whole-genome re-sequencing data from one affected and 289 unaffected animals revealed a 1-bp deletion (g.15079217delC, rs723240647) in the coding region of the GON4L gene that segregated with the dwarfism-associated haplotype." (PMID 27036302, 2016).
Li-Takada-Miyake syndrome (1 paper, 2026). "Zebrafish gon4la mutants provide a tractable vertebrate model for dissecting mechanisms of GON4L-related developmental disorder, Li-Takada-Miyake syndrome (LTMS), and for functional testing of rare GON4L variants." (PMID 41935090, 2026).
microcephaly (1 paper, 2026). A congenital or acquired developmental disorder in which the circumference of the head is smaller than normal for the person's age and sex. "Biallelic mutations in human GON4L have been linked to short stature, craniofacial abnormalities, and microcephaly, yet the underlying mechanisms remain unclear." (PMID 41935090, 2026).
cancer (1 paper, 2016). A tumor composed of atypical neoplastic, often pleomorphic cells that invade other tissues. "Other recurrent mutation targets that have been implicated in different types of cancers included PPM1D and GON4L." (PMID 27224912, 2016).
tumor (1 paper, 2022). "Among them, GON4L is a transcriptional regulator gene that has been reported to drive tumor growth through the YY1-androgen receptor-CD24 pathway." (PMID 36120364, 2022).
GON4L also shares sentences with these, for which no sentence is quoted: COVID-19 (1 paper); growth disorders (1); sterility (1).